NDUFS4 (NADH:ubiquinone oxidoreductase subunit S4)
Diseases named in the same sentence as NDUFS4 in open-access papers (continued):
Sharing a sentence is not in itself a finding about the gene and the disease.
schizophrenia (1 paper, 2023). A major psychotic disorder characterized by abnormalities in the perception or expression of reality. "In contrast, the mRNA expression of NDUFB2, NDUFB5, and NDUFS4 was decreased in the hippocampus and the mRNAs of NDUFV1, NDUFV2, and NADUFS1 in the striatum of patients with schizophrenia." (PMID 37107350, 2023). "Specifically, mRNA levels of Ubiquinone Oxidoreductase Core Subunit V1 (NDUFV1), NDUFA8, NDUFB9, NDUFS4, NDUFS7, and NDUFV2 were decreased in the frontal cortex of patients with schizophrenia compared with controls." (PMID 37107350, 2023).
viral infection (1 paper, 2025). "Confocal imaging of IAV-infected WT and Ndufs4 KO LET1 cells treated with 2DG or DCA revealed reduced SNA and IAV HA staining, consistent with decreased surface sialylation and viral infection." (PMID 40614187, 2025). "Prompted by the viral infection-induced rise in surface SIA, we next investigated whether this change translates into enhanced IAV attachment in Ndufs4 KO cells." (PMID 40614187, 2025).
viral pneumonia (1 paper, 2025). Inflammation of the lung parenchyma that is caused by a viral infection. "To better understand how mitochondrial dysfunction influences viral pathogenesis, we infected Ndufs4 KO and wild-type (WT) mice with mouse-adapted IAV, X31, at postnatal age 30 (P30) using a whole-body inhalation exposure system to produce viral pneumonia." (PMID 40614187, 2025).
mitochondrial disease (26 papers, 2014 to 2025). "Defects in NDUFS4 are a major cause of CI deficiency-associated mitochondrial disease in humans and the mouse and D. melanogaster animal models display CI deficiency and pathological phenotypes." (PMID 37823874, 2023). "Administration of isoform-specific PKCδ inhibitors to NDUFS4-deficient mice will define the relevance of this protein as a target for the treatment of mitochondrial disease." (PMID 32850799, 2020). "Here, we utilized the Ndufs4−/− mice to test the hypothesis that Complex I deficiencies may alter normal iron distribution which contributes to mitochondrial disease progression." (PMID 36799301, 2023). "In the next phase of this study, we measured NAD(H) levels in Ndufs4-KO mice, a well-established animal model for studying typical mitochondrial diseases, using the same method." (PMID 39858433, 2024). "Control Ndufs4−/− mice showed decreased levels of Tfr1 mRNA in liver by qRT-PCR relative to WT mice, consistent with increased labile iron in the mitochondrial disease mice." (PMID 36799301, 2023). "In response to preclinical data from the Ndufs4(KO) mouse (detailed below), mechanistic target of rapamycin (mTOR) inhibitors have also recently been tested in small cohorts of mitochondrial disease patients." (PMID 36056365, 2022). "The effect of rapamycin has been tested in NDUFS4 KO mice, with results from this and other studies showing that mTORC1 inhibition alleviated mitochondrial disease in the mouse model of LS." (PMID 34456746, 2021). "Because mitochondria are central in the consumption of oxygen and the production of energy, it is unsurprising that changes in atmospheric oxygen have been shown to modify disease phenotypes in NDUFS4 KO mice, and in a worm model of mitochondrial disease." (PMID 27741510, 2016). "Ndufs4 KO mice have decreased Complex I levels and activity in multiple tissues and show severe and progressive symptoms of mitochondrial disease that mirror human LS." (PMID 26257774, 2015). "Importantly, mTOR activity was found to be hyperactive, and rapamycin rescued grip strength and metabolic defects, supporting a role for mTOR in mitochondrial disease beyond Ndufs4(KO)." (PMID 36056365, 2022). "Ndufs4(−/−) mice are born healthy, as are many patients with mitochondrial disease, with no overt symptoms of neurologic dysfunction before disease onset." (PMID 37770252, 2023). "Here, we exposed Ndufs4(−/−) mice to varying concentrations of isoflurane at pre- and post-disease onset ages to directly assess the impact of anaesthesia with VAs in ETC CI mitochondrial disease." (PMID 37770252, 2023). "By knocking down ND-18, the unique Drosophila ortholog of NDUFS4, an accessory subunit of the NADH:ubiquinone oxidoreductase (Complex I), we developed and characterized several dNDUFS4 models that recapitulate key features of mitochondrial disease." (PMID 29590638, 2018). "In 2 mitochondrial disease models, hypoxia corrects defects that arise as a consequence of the genetic lesion—decreasing excessive molecular oxygen in the setting of a defective ETC in Ndufs4 knockout and restoring iron sulfur cluster levels in frataxin knockout." (PMID 37220109, 2023). "Thus, it is possible that lack of NDUFS4 may lead to widespread interneuron development, in line with reports suggesting neurodevelopmental alterations in mitochondrial disease models." (PMID 41321311, 2025).
neurodegenerative disease (10 papers, 2017 to 2026). A disorder of the central nervous system characterized by gradual and progressive loss of neural tissue and neurologic function. "Knockout of Ndufs4-induced complex I deficiency triggers ROS generation and lipid droplet accumulation in glia, and subsequent neurodegenerative disease in mice." (PMID 33323934, 2020). "We previously reported that hypoxia improves survival and reverses neurodegenerative disease in Ndufs4−/− mice." (PMID 30520688, 2019). "Ndufs4−/− mice (knockout mice) develop a progressive neurodegenerative disease and die ~60 days after birth." (PMID 30520688, 2019). "It thus suggests the Ndufs4−/− mouse model may also be useful to provide insights into age-related neurodegenerative diseases or in the discovery of effective interventions for AD." (PMID 40467953, 2025). "Given its role in mitochondrial function and neurodegeneration, Ndufs4 could be a potential target for therapeutic intervention in age-related cognitive decline and neurodegenerative diseases." (PMID 39596610, 2024). "To assess whether isoflurane toxicity is contingent on the presence of overt neurodegenerative disease, we exposed pre-disease onset Ndufs4(−/−) mice at age P30 to 30 min per day isoflurane 0.4%, O2 100%, or air." (PMID 37770252, 2023). "This knowledge may be useful in understanding the pathophysiological aspect of neurodegenerative diseases but, further clear understanding of molecular mechanism of Ndufs4 is quite essential." (PMID 34040028, 2021).
tumor (7 papers, 2019 to 2025). "Interestingly, recent findings indicate that loss of NDUFS4 can also influence tumor immunity." (PMID 41157129, 2025). "In contrast, genetic ablation of NDUFS4 enhanced tumor immunogenicity and restricted tumor growth in vivo, underscoring a role for Complex I in modulating antitumor immunity." (PMID 41157129, 2025). "Another study reported the reduced expression of NDUFS4, SDHA, UQCR2, MT-CO1, and ATP5F1A in tumor samples from 94 PCa patients who had undergone radical prostatectomy after tumor diagnosis." (PMID 36901912, 2023).
cancer (5 papers, 2018 to 2025). A tumor composed of atypical neoplastic, often pleomorphic cells that invade other tissues. "Surprisingly, both confirmed mtFE markers as well as one mito marker (i.e. Ndufs4) were annotated by CCGD database as potential cancer drivers of HCC in mice." (PMID 31061415, 2019). "For NDUFS4, both GS 7 and 9 carcinomas showed significantly higher expression than GS 6 and 8 tumors." (PMID 30538797, 2018). "The genes encoding the metabolic enzymes for oxidation phosphorylation such as Atp5l, Cox4i1, Cox5a, Cox7a2, Ndufc2, Ndufs4, Sdhd, Uqcrq28 were significantly downregulated in 20(S)/(R)-Rh2E2-treated LLC-1 cancer cells, but not in normal cells." (PMID 32796841, 2020).
neurological disease (5 papers, 2019 to 2025). "Continuous exposure of Ndufs4−/− mice to normobaric 11% O2 prevents the development of neurological disease and markedly improves survival." (PMID 30520688, 2019). "Breathing normobaric 11% O2 prevents neurological disease and improves survival in Ndufs4−/− mice." (PMID 30520688, 2019).
infection (2 papers, 2023 to 2025). The state of being infected such as from the introduction of a foreign agent such as serum, vaccine, antigenic substance or organism. "Notably, citrate (M+2) labeling increased in WT cells following infection, whereas Ndufs4 KO cells showed elevations at baseline that rose even further with infection." (PMID 40614187, 2025). "Notably, around 20% of Ndufs4 KO mice died shortly after infection was induced." (PMID 40614187, 2025). "Given the enrichment of glycolytic pathways in Ndufs4 KO LET1 cells at baseline and during infection, we next assessed glucose uptake potential by measuring glucose transporter 1 (GLUT1) expression using immunofluorescence microscopy." (PMID 40614187, 2025). "In this study, we successfully constructed Ndufs4 siRNA, the TCID50 was 1 × 1010 PFU/mL and transfected H9c2 was over 90% after 72 hours of infection." (PMID 36741296, 2023).
cardiac disease (1 paper, 2025). "In Ndufs4 knockout mice, CCH dramatically extended lifespan, but the mice still succumbed at one year, likely due to cardiac disease." (PMID 39841808, 2025). "Although CCH does not appear to alleviate cardiac disease in the shFxn or Ndufs4 knockout models, a continuous hypoxia regimen which included two weeks at 7% oxygen did promote recovery of the left ventricle after left anterior descending artery ligation in mice." (PMID 39841808, 2025).
kidney diseases (1 paper, 2024). "Further studies and a comprehensive exploration of the impact of other subunits of CI on progression of DKD are needed to better define the role of Ndufs4 on progression of DKD and other kidney diseases." (PMID 38438382, 2024).
NDUFS4 also shares sentences with these, for which no sentence is quoted: Failure to thrive (3 papers); mitochondrial neurogastrointestinal encephalomyopathy (3); alopecia (2); cerebellar ataxia (2); adenoma (1); Amoebiasis (1); atherosclerosis (1); Barth syndrome (1); Blindness (1); brain disease (1); breast tumor (1); cardiac arrhythmia (1); ethylmalonic encephalopathy (1); Friedreich ataxia (1); Huntington disease (1); Hypoglycemia (1); legionellosis (1); leukodystrophy (1); Leukoencephalopathy (1); lung carcinoma (1); Mitochondrial myopathy (1); myocardial infarction (1); myopathy (1); neuromuscular disease (1); Non-alcoholic fatty liver disease (1); Obesity (1); optic atrophy (1); Optic neuropathy (1); OXPHOS disease (1); prostate carcinoma (1).
A further 4 diseases each share a sentence with NDUFS4 in 1 paper.